MTOR (mechanistic target of rapamycin kinase)
Diseases named in the same sentence as MTOR in open-access papers (continued):
Sharing a sentence is not in itself a finding about the gene and the disease.
cancer (continued). "The signaling pathways of Ras-Raf-MEK-ERK, Abl, Src, c-Kit, Wnt-GSK3 and PI3K-Akt-mTOR are considered typically important in cancer cell growth and survival." (PMID 32572057, 2020). "Given the role of mTOR in promoting protein translation, cell growth and proliferation, it is an attractive target for cancer therapy." (PMID 32054043, 2020). "Currently, temsirolimus and everolimus (mTOR inhibitors) are approved for use in Europe and the United States in a variety of cancer-related indications and are routinely used in oncology practices as an alternative to traditional cytotoxic chemotherapy." (PMID 31586300, 2020). "Overexpression of CXCL7 is associated with poor prognosis in several cancers and connected to tumor growth, invasion, migration and angiogenesis by motivating the PI3K/AKT/mTOR signaling pathways." (PMID 33643903, 2020). "Conversely, glucose restriction can inhibit various energy‐dependent pathways such as IGF‐1/PI3K/Akt/mTOR in cancer cells, suppress cell metabolism and growth, and promote G1 phase arrest and apoptosis." (PMID 32678516, 2020). "Studies have suggested that activation of ROS/JNK and inhibition of the AKT/mTOR signaling pathway can effectively induce apoptosis and autophagy in cancer cells." (PMID 32308804, 2020). "Several works have revealed that one of the major growth regulatory pathways controlled by LKB1-AMPK is the mammalian target-of-rapamycin (mTOR) pathway that controls cell growth in all eukaryotes and is deregulated in most human cancers." (PMID 32365882, 2020). "The mammalian target of rapamycin (mTOR) signaling pathway is important for cell growth, leading to the facilitation of cancer progression." (PMID 32111101, 2020). "The dimeric form of PKM2 has a lower activity and is predominantly expressed in cancer cells due to mTOR activation." (PMID 32992783, 2020). "Consistent with previous literature, we did not observe differences in the Ras/Raf/MEK/MAPK and PI3K/Akt/mTOR pathways as they have greater influence in HER2+ cancer." (PMID 32408199, 2020). "The activity of mTOR in neoplasms is often deregulated, which leads to increased proliferation, migration of cancer cells and an increase in the synthesis of nucleotides and proteins." (PMID 33114763, 2020). "A recent finding implicated mTORC1 and mTORC2 as key regulators of EMT, and knockdown of mTORC1 and mTORC2 induced mesenchymal-to-epithelial transition, while inhibition of mTOR signaling suppressed cancer cell migration and invasion." (PMID 32498358, 2020). "Downstream of Akt, IκB kinase α (IKKα) can phosphorylate mTOR at Ser 1415 promoting mTORC1 activity increasing cell proliferation in cancer cells." (PMID 32854217, 2020). "In our study, we have revealed that constitutive upregulation of mTOR signaling not only drives resistance of cancer cells to chemotherapy and targeted drugs, but also generates a druggable metabolic vulnerability that can be therapeutically exploited." (PMID 32943635, 2020). "This supports the possibility of reviving clinical development of mTOR inhibitor-based approaches for cancer prevention with particular focus on the importance of drug dose." (PMID 32341756, 2020). "Our group discovered that mTOR signaling in cancer cells determines the MDSC accumulation through regulating G-CSF production." (PMID 33343560, 2020). "ATP depletion by OxPhos inhibition using phenformin and gossypol, therefore, inactivates mTOR, which leads to drug-resistant cancer cell death by blocking autophagy." (PMID 32883024, 2020). "Tumour suppressor factors are negatively regulated by mechanistic target of rapamycin (mTOR) resulting in the induction of autophagy and suppression of the cancer initiation." (PMID 32935427, 2020). "We found that anticancer drugs induce the autophagy process for supplying nutrients, such as amino acids and ATP, which then activates the mTOR pathway, promoting cancer growth through biosynthesis." (PMID 32883024, 2020).
cancer (continued). "Following neddylation blockade, we discovered that induction of ZEB1 was mediated by HIF-1α through the activation of the PI3K/Akt/mTOR pathway, emphasizing the role of neddylation in cancer migration." (PMID 33097763, 2020). "Oncogenic activation of mTOR signaling induces several processes required for cancer cell growth, survival, and proliferation and significantly increases the malignancy of cancer cells." (PMID 33123313, 2020). "We conducted both wound healing assay and transwell assay by co-treating with MLN4924 and inhibitors of PI3K/Akt/mTOR in all three cancer cell lines." (PMID 33097763, 2020). "Cancer cell growth is largely dependent on lipid metabolic processes, which are tightly controlled by mTOR signalling, a pathway that is commonly perturbed in cancers." (PMID 33318517, 2020). "The PI3K-Akt-mTOR axis is indispensable for modulation of cancer-related behaviors including cell vitality, proliferation, and cell cycle control; the mutations of which is commonly detected in tumor, thereby making it promising therapeutic targets." (PMID 32596285, 2020). "One of the general chemopreventive strategies includes inhibition of the PI3K/Akt/mTOR pathway that is responsible for the proliferation of cancer cells." (PMID 32429547, 2020). "Secreted Phosphoprotein 1 (SPP1), also known as osteopontin, is one of the molecules in the PI3K/AKT/mTOR pathway, and it has been reported as an oncogene in many cancers." (PMID 33193731, 2020). "Up-regulation of the PI3K/AKT/mTOR pathway, and increased glucose consumption via glycolysis, offer evolutionary advantages to cancer cells in normoxia as well as hypoxia." (PMID 31904088, 2020). "It is well known that both mTOR signing pathway and MAPK signaling pathway are two of the most implicated cellular pathways in cancers." (PMID 32680494, 2020). "The mTOR pathway is one of the most deregulated signaling pathways in human cancer, and constitutive activation of mTORC1 is very frequently observed in different tumors." (PMID 32708484, 2020). "Activation of MTOR signaling was shown to confer multiple cancer types with resistance to chemo-radiation." (PMID 33330109, 2020). "In primary tumors mTOR can confer many growth advantages to cancer cells or progenitor stem cells, such as promoting cell proliferation and resistance to apoptosis." (PMID 33362215, 2020). "Further studies are necessary to assess the potential effect of conversion from CNIs to mTOR inhibitors on both rejection and cancer." (PMID 33162990, 2020). "These agents can completely shut down the whole PI3K-Akt-mTOR pathway, resulting in better anti-cancer activity." (PMID 33154352, 2020). "The AKT protein is central to the proliferation and survival of normal and cancer cells, and its downstream protein, mTOR, also plays an indispensable role in the cellular processes." (PMID 32384682, 2020). "Mammalian target of rapamycin (mTOR) is a serine/threonine protein kinase that regulates the proliferation, death, survival and protein synthesis of cancer cells." (PMID 32116708, 2020). "In human, as mTOR hyperactivation is a common feature of cancers, mTOR inhibitors are becoming a therapeutic target in certain type of cancers." (PMID 31947601, 2020). "Conversely, treatment with mammalian target of rapamycin (mTOR) inhibitors, such as sirolimus, has been shown to reduce the incidence of cancer." (PMID 32605413, 2020). "Over the last few years, owing to regulating mTOR naturally and negatively, Deptor has become the focus of research on the occurrence and development of human malignant tumours." (PMID 32510855, 2020). "It is well-known that Akt/mTOR signaling pathway was frequently activated in cancer and controlled cell metabolism and growth." (PMID 32363163, 2020). "The evidence of enhanced mTOR signaling in cancer led to the development of novel mTOR inhibitors that are used in cancer treatment." (PMID 32012648, 2020).
cancer (continued). "Glutamine also plays a crucial role in the uptake of essential amino acid and in maintaining the activation of target of rapamycin (TOR) kinase, which is the central component of the well-known cancer pathway mTOR." (PMID 33372594, 2020). "It is downregulated in human cancers, which leads to the upregulation of mTOR and insulin-like growth factor receptor type 1 (IGF1R) in cancer tissue." (PMID 33023154, 2020). "It is well established that mTOR signaling, a critical protein in regulating cancer cells, takes part in varieties of fundamental biological activities containing cell death, autophagy, metabolic reprogramming, cell growth, and cell cycle." (PMID 32099529, 2020). "Accordingly, dysregulation of mTOR (mammalian or mechanistic TOR) signaling in humans has been implicated in a myriad of diseases including metabolic syndrome, cancer and neurodegenerative diseases." (PMID 32759652, 2020). "Evidence has shown that oncogenic activation of mammalian target of rapamycin (mTOR) signaling induces cellular processes required for cancer cell growth and survival." (PMID 32576196, 2020). "In many malignant tumors, the PTEN gene has suffered mutations, resulting in abnormal PTEN, which cannot exert its inhibitory effect on the PIP3/AKT/mTOR pathway." (PMID 33375317, 2020). "Metformin is well known for its activation of AMPK and one of the mechanisms of preventing cancer is through its activation of AMPK resulting in the inhibition of mTOR." (PMID 33193076, 2020). "Overall, these researches have provided clues that andrographolide dualistically regulated mTOR pathway in different cancers." (PMID 32759728, 2020). "Studies have shown that the AKT/mTOR signaling pathway inhibits autophagy death of cancer cells by regulating the transcription and translation of growth promoting oncogenes or proteins." (PMID 33143000, 2020). "The PI3K/AKT/mTOR pathway has been explored extensively to develop therapeutic strategies for different types of cancers." (PMID 33292283, 2020). "Rapamycin is the first mTOR inhibitor to be isolated and has extensively been studied in its ability to extend lifespan, decrease cancer, and have immunosuppressant effects." (PMID 32127537, 2020). "FGF1 activation is mediated via the PI3K-Akt signaling pathway that lies upstream of mTOR, which is related to autophagy, apoptosis and metabolism of cancer cells, as well as the NLRP3-mediated inflammatory response." (PMID 32615540, 2020). "The mTOR pathway also had a relatively high rate of alterations in GI cancer (75%), with an alteration frequency of 95%, 74%, 62%, 86% and 70% among the five cancer subtypes, respectively." (PMID 32863943, 2020). "It appears that miR-205 is able to target the Akt/mTOR signaling pathway to regulate malignancy and progression of cancer cells." (PMID 32664703, 2020). "The AKT/mTOR pathway also plays a remarkable role in the regulation of epithelial-to-mesenchymal transition (EMT) in cancer." (PMID 32384682, 2020). "Pathways relative to “cancer,” “apoptosis,” “hedgehog signaling,” “mTOR signaling,” and “mismatch repair” were identified among those shared between ODs and CDs." (PMID 33376724, 2020). "Dual PI3K/mTOR inhibition consistently demonstrated radiosensitisation of all types of cancer cells." (PMID 32443649, 2020). "Multiple studies have suggested that inhibiting the activity of mTOR blocks the cycle of cancer cells and further inhibits proliferation." (PMID 33658929, 2020). "The PI3K/AKT/mTOR is an important pathway in cancer related with competitive growth, survival, increase metastatic ability and resistance to conventional therapy and also has been explored for canine oncology." (PMID 33230132, 2020).
cancer (continued). "These miRNAs target the PI3K-Akt signaling pathway, transcriptional misregulation in cancer, pathways in cancer, and mTOR signaling pathway, which are among the target pathways significantly affected in F2-gonad tissues." (PMID 33133155, 2020). "In summary, it is convincing that crosstalk between Hh and mTOR signaling in cancer cells exist, but the mechanisms are far from clear." (PMID 33081032, 2020). "The increasing number of evidences suggest the pivotal role of the AKT/mTOR pathway in chemoresistance and radioresistance in cancer cells." (PMID 32384682, 2020). "The upregulation of mTOR signaling has tumor-inducing potential by promoting its growth and progression and the aberrant regulation of mTOR has been observed in a variety of cancers." (PMID 33297429, 2020). "Due to the dysregulation of upstream tumor suppressors or oncogenes, such as PTEN, TSC1/2, PI3K, or IRS1, AKT/mTOR signaling is frequently activated in various cancers." (PMID 33204686, 2020). "The crucial molecules PIK3CA, AKT1, PTEN, and mTOR in the PI3K/Akt and mTOR pathways were all frequently dysregulated in different types of cancer." (PMID 32863943, 2020). "It has been shown that activation of the PI3K/Akt/mTOR pathway plays crucial roles in cancer development and progression." (PMID 32606352, 2020). "The results of PLB-induced PI3K/Akt/mTOR signal pathway inhibition in rat ovarian granulosa cells are consistent with the findings obtained with other cancer cell lines." (PMID 33029296, 2020). "Given the importance of the mTOR pathway in cancer, these results provided one of the links between TCTP and tumorigenicity." (PMID 32645936, 2020). "mEAK-7 is expressed predominantly in metastatic human cancer and forms a novel mTOR complex involving DNA-PK to promote S6K2 signaling and suppress 4E-BP1." (PMID 33364499, 2020). "Related mechanism studies show that ribosome biosynthesis is an important part of Ras/Raf/MEK/ERK, MYC, and PI3K/Akt/mTOR pathways, which are proven to drive malignant tumors." (PMID 33584809, 2020). "It has been acknowledged that AKT/mTOR pathway performs essential part in regulating cancer cell biological activities such as proliferation and migration, including in CC." (PMID 31682716, 2020). "The mTOR signaling pathway is involved in cell metabolism and proliferation, which are key hallmarks of cancer and allow for HCC development, progression and spreading." (PMID 32070029, 2020). "mTOR, a highly conserved serine/threonine kinase is often detected in cancers and is regulated by various upstream regulators such as, PI3K and AKT8,9." (PMID 33116125, 2020). "PP242 is an ATP-competitive second-generation inhibitor of mTOR that exerts its anticancer activity on numerous types of cancer." (PMID 33067464, 2020). "Data from DNA sequence analysis implies that the phosphatidylinositol 3-kinase PI3K-Akt-mTOR pathway is also frequently involved in the cancer development." (PMID 31913295, 2020). "The phosphatidylinositol 3-kinase (PI3K) pathway is a key regulator of cellular physiology, and PI3K/AKT/mTOR signaling is known to enhance tumor cell proliferation, survival and motility in various cancers." (PMID 33110476, 2020). "Recent reviews have demonstrated that many cancers have increased mTOR activity due to deregulation of upstream and downstream mTOR signal pathways." (PMID 32495998, 2020). "In conclusion, we report that eEF-2K contributes to the activation of resistance signaling pathways of mTOR inhibitor, suggesting a novel strategy to enhance mTOR-targeted cancer therapy through combining mitoxantrone, an eEF-2K inhibitor." (PMID 33144562, 2020).
cancer (continued). "Since activation of mTOR plays a crucial role in maintaining growth and inducing metastasis in many cancers, it has been intensively studied as a potential target for cancer therapy." (PMID 32971982, 2020). "This identifies a druggable vulnerability of therapy-refractory cancer cells with mTOR-dependent drug resistance." (PMID 32943635, 2020). "Radioresistance is another phenomenon in cancer cells where the AKT/mTOR pathway plays a significant role." (PMID 32384682, 2020). "For instance, sanggenol triggers apoptosis and cell cycle arrest in cancer cells via inhibition of the PI3K/Akt/mTOR axis." (PMID 32380783, 2020). "AKT/mTOR signaling is one of the main regulatory pathway in cancer cells that negatively regulates autophagy." (PMID 33013353, 2020). "Metformin indirectly reduces mammalian target of rapamycin (mTOR) signaling, which inhibits cancer cell growth and proliferation." (PMID 34095407, 2020). "mTOR is considered an important biomarker, with recently developed mTOR inhibition strategies having achieved significant success in cancer treatment." (PMID 33234722, 2020). "As a central node in the PI3K/AKT/mTOR pathway, which regulates various processes considered to be hallmarks of cancer, this kinase has become a prime target for cancer therapy." (PMID 33045011, 2020). "The PI3K/AKT/mTOR pathway is one of the most frequently activated signaling pathways in cancers and is responsible for tumor development, cellular metastasis, and proliferation." (PMID 32373608, 2020). "The activation of mTOR increases the rate of protein synthesis and suppresses autophagy in cancer cells." (PMID 32012648, 2020). "The mammalian target of rapamycin (mTOR), a serine/threonine kinase that regulates cell growth and metabolism, is frequently activated in human cancers." (PMID 32899752, 2020). "The importance of upregulation, increased activation and constitutive signaling of the PI3K/Akt/mTOR pathway in cancer is well documented." (PMID 31989769, 2020). "Reactivation of the MEK/ERK axis in cancer cells addicted to inhibition of the Hippo/MST pathway through the PI3K/AKT/MTOR signaling pathway can be beneficial for therapy efficiency after targeted PI3K blockade." (PMID 32375238, 2020). "Many developmental pathways (including NOTCH, Wnt/β-Catenin, Sonic Hedgehog, EGFR/PI3K/Akt/mTOR pathways) that maintain the self-renewal property of cancer stem-like cells have been identified." (PMID 35692625, 2020). "Cancer-associated PTEN mutations are loss of function mutations, leading to the upregulation of the PI3K/Akt/mTOR pathway, abnormal cell proliferation, and metabolic changes." (PMID 31952362, 2020). "mTOR signaling is often aberrantly hyperactivated in various types of cancer cells in response to the abundant cellular ATP to promote tumor cell proliferation." (PMID 32782783, 2020). "As a valuable cancer therapy targets, mTOR signaling pathway has mainly modulated cancer cell autophagy or induced apoptosis." (PMID 32513155, 2020). "The PI3K/AKT/mTOR pathway drives cell proliferation, motility, and migration in a variety of malignancies." (PMID 32850947, 2020). "The mTORC1 signal is currently attracting attention as a target for drug discovery, and mTOR inhibitors such as everolimus are actually in use as molecular-targeted drugs for various cancers." (PMID 32486221, 2020). "There are no mechanistic studies for how low ECM stiffness promotes cancer stemness, while high ECM stiffness activates the Akt/mammalian target of rapamycin (mTOR) signalling pathway in an integrin β1-dependent manner to promote cancer stemness." (PMID 32231294, 2020). "Chronic exposure to DSS in a model of azoxymethane (AOM)–DSS colitis-induced cancer led to HSF1-dependent activation of mTOR and increased glutaminolysis in cancer cells, and promoted tumor growth." (PMID 33288768, 2020).